RAB35 (RAB35, member RAS oncogene family)
Diseases named in the same sentence as RAB35 in open-access papers (continued):
Sharing a sentence is not in itself a finding about the gene and the disease.
infection (14 papers, 2014 to 2024). The state of being infected such as from the introduction of a foreign agent such as serum, vaccine, antigenic substance or organism. "In fact, upon loss of Rab35, higher lethality after infection was observed, whereas the Rab35 mutant flies showed defects in phagocytosis in vivo." (PMID 31035701, 2019). "Indeed, depletion of Rab35 phenocopied the exacerbated interferon responses observed during infection with CpoS-deficient mutants." (PMID 37530528, 2023). "Since Rac1 and Rab35 were able to recover the cell shape and migration phenotypes produced by Prpk deficiency, we also examined the rate of survival to infection in flies co-expressing each protein with the Prpk-IR construct." (PMID 35721516, 2022). "We also examined whether Rab35 is associated with intracellular UPEC during in vivo infection using a well-established murine UTI infection model." (PMID 26248231, 2015). "Interestingly, similarly to ATG16L1 and LC3, which associate with both QIRs at 2 weeks post-infection and with IBCs at 6 h post-infection, we found that Rab35 also colocalized with immature IBCs at 6 h post-infection." (PMID 26248231, 2015). "SERPINE1, STX4 and SEC31A, along with RAB35, are also involved in membrane trafficking and the innate immune response, which is an important initial host response to infection of cells with Chlamydia bacteria." (PMID 35510793, 2022). "Therefore, as Rab35 is a key regulator of phagocytosis by controlling Rac1 and Cdc42 transport to the plasma membrane and actin structure remodelling, alteration of the Rab-Rho coordination could be responsible for higher susceptibility to infections." (PMID 31035701, 2019). "As such, it is the interactions with ARF6 and Rab35 that are relevant for EspG's function during infection." (PMID 27261256, 2016). "Our data suggests that during infection EspG is recruited to ARF6/Rab35 positive endosomal structures through scaffolding with GTP-bound ARF6." (PMID 27261256, 2016). "Here we report that EspG interacts specifically with the small GTPases ARF6 and Rab35 during infection." (PMID 27261256, 2016). "Our investigation of the small GTPase interacting partners of EspG during infection reveals that EspG modulates an ARF6:Rab35 signaling axis to disrupt recycling endosome function, resulting in the accumulation of recycling cargo within the host cytosol." (PMID 27261256, 2016). "These experiments demonstrate that UPEC exploits Rab35 and TfR1 to acquire iron during later stages of intracellular infection (≥ 24 h) in bladder cells." (PMID 26248231, 2015). "We first determined the levels of several genes known to be involved in iron acquisition in UPEC (feoA, tonB, entE, fepA, exbB, sitA, chuA, iroN, and iroB) at 24 h post-infection in Rab35-sufficient BEC cells by qRT-PCR analysis." (PMID 26248231, 2015). "We also measured the levels of UPEC that are expelled from Rab35 silenced cells at 4 h and at 24 h post-infection." (PMID 26248231, 2015). "The percentage of UCV positive for Rab35 continuously increased throughout the course of infection further highlighting the requirement of this pathway for UPEC persistence within bladder cells." (PMID 26248231, 2015). "We also found an increase in the expression of Rab35 mRNA (2.2 fold at 24h, p = 0.008) as well as protein (3 fold at 24h, p = 0.005) with the progression of infection." (PMID 26248231, 2015). "Quantitation of Rab11a/Rab35-positive CCVs revealed that while Rab11a interacts with the CCV more at 3 dpi, Rab35 is significantly more prevalent at CCVs at 6 dpi, suggesting that the CCV preferentially interacts with Rab11a and Rab35 depending on the stage of infection." (PMID 38841112, 2024). "Several other Rabs displaying close phylogenetic relationship to Rab1, including Rab8, Rab18, Rab35, Rab33, Rab30, Rab19, and Rab37, could also be modified by SseK3 upon infection." (PMID 32504010, 2020).
infection (continued). "In light of these findings, we hypothesized that AnkX manipulates endocytic recycling during infection of macrophages by targeting Rab35." (PMID 28944216, 2017). "Therefore, whilst EspG is able to interact with and induce GTP hydrolysis of both Rab1 and Rab35 in vitro, spatial restriction of EspG to endosomal compartments during infection appears to direct EspG's GAP activity towards Rab35." (PMID 27261256, 2016). "However, we observed that in Rab35-deficient cells, a significantly higher number of intracellular UPEC colocalized with lyso-Tracker Red at 24 h post infection." (PMID 26248231, 2015). "To test this, we first examined whether TfR1 and Rab35 protein colocalized with UCV during infection." (PMID 26248231, 2015). "We hypothesized that Rab35 might play a role in iron acquisition during intracellular infection by UPEC." (PMID 26248231, 2015). "In addition, we also found that the levels of mature/activated form of cathepsin D increased in Rab35 knockdown cells with the progression of infection." (PMID 26248231, 2015). "Therefore, Rab35 recruitment is a key feature of the UPEC strategy for exploiting host vesicular trafficking during intracellular infection." (PMID 26248231, 2015). "Further highlighting the association between Rab35 and TfR1 during UPEC infection, we found that similar to Rab35 knock down cells, the reduced iron pool in TfR1 knockdown cells was also associated with reduced survival of UPEC at 24 and 48 h post infection (3.4 fold at 24 h, p = 0.02)." (PMID 26248231, 2015). "A notable exception was the depletion of Rab35, which compromised the ability of CTL2 to dampen luciferase production to a level similar to that induced by infection with CTL2-cpoS::cat." (PMID 37530528, 2023). "Remarkably, we found that silencing of Rab35 led to a significant reduction in the intracellular bacterial load of BEC5637 cells at 24 and 48 h post infection (3.3 fold at 24 h, p = 0.01 and 2.5 fold at 48 h, p = 0.04)." (PMID 26248231, 2015). "In Rab35-silenced cells, five of the UPEC genes tested were up-regulated at 24 h post-infection: exbB, entE, fepA, chuA, and feoA." (PMID 26248231, 2015). "After 2 h of infection, the percentage of SCV positive for Rab8 or Rab35 decreased to less than 5%." (PMID 34815429, 2021). "During infection, this results in the Rab GAP activity of EspG being directed towards Rab35." (PMID 27261256, 2016). "Intriguingly, the expression of the two genes sitA and iroB that were up-regulated in infected control cells were found to be either down-regulated (sitA) or did not change significantly (iroB) in Rab35 silenced cells at 24 h post-infection." (PMID 26248231, 2015). "There was no change in the % of UPEC expelled from Rab35 silenced cells compared to control at 4 h post-infection." (PMID 26248231, 2015). "At 24 h post-infection, there were reduced levels of UPEC expulsion from Rab35 silenced cells." (PMID 26248231, 2015). "Rab35 is involved in the fast recycling of TfR, the protein critical for the cellular uptake of iron, and UPEC is known to up-regulate TfR1 levels during intracellular infection of BEC." (PMID 26248231, 2015). "We previously reported that endosome-resident RAB35 and TBC1D9 recruit NDP52 for triggering xenophagy, and thus a highly sophisticated mechanism may exist for regulating autophagy receptors in response to infection." (PMID 33425778, 2020). "However, it is not yet known why AnkX targets Rab35 during infection." (PMID 28944216, 2017). "In order to confirm that the reduced uptake of transferrin was not due to a general defect in endocytosis due to infection, we analyzed the uptake of a lipid (MFI Bodipy) in Rab35 silenced cells." (PMID 26248231, 2015). "Interestingly, silencing of TfR1, but not Rab35, also reduced the LIP at 4 h post-infection, although UPEC load was unaffected at this time point." (PMID 26248231, 2015).
neurodegenerative disease (2 papers, 2018 to 2023). A disorder of the central nervous system characterized by gradual and progressive loss of neural tissue and neurologic function. "Recent studies have suggested associations between RAB35 and neurodegenerative diseases." (PMID 37085665, 2023). "Further characterization of the physiological and pathological functions of RAB35 will provide a better understanding of the molecular pathology of neurodegenerative diseases." (PMID 37085665, 2023).
neurodevelopmental disorder (2 papers, 2023 to 2024). A behavioral and cognitive disorder with onset during the developmental period that involves impaired or aberrant development of intellectual, motor, or social functions. "The encoded protein, Rab35, functions in abscission of the cytokinetic bridge and in primary cilia formation and signaling, phenotypes associated with neurodevelopmental disorders." (PMID 38432637, 2024). "Previous investigations have reported patients with variants of RUSC2, a Rab35 effector, which present with a neurodevelopmental disorder." (PMID 38432637, 2024). "Our findings provide evidence of altered Rab35 function as a causative factor of a neurodevelopmental disorder." (PMID 38432637, 2024). "Rab35 is involved in synaptic vesicle transport, and synaptic disturbance is recognized as a molecular disruption in various neurodevelopmental disorders, including ASD." (PMID 37520045, 2023). "In addition, variants in a Rab35 GAP, TBC1D24, have been associated with a spectrum of neurodevelopmental disorders in a cohort of patients." (PMID 38432637, 2024).
RAB35 also shares sentences with these, for which no sentence is quoted: multiple system atrophy (2 papers); neurological disease (2); non-small cell lung carcinoma (2); progressive supranuclear palsy (2); adenocarcinoma (1); Autoimmunity (1); bacterial infection (1); developmental delay (1); Huntington disease (1); metastatic cancers (1); pancreatic cancer (1); Parkinsonism (1); schizophrenia (1); spinocerebellar ataxia (1).